TGFBR1 (transforming growth factor beta receptor 1)
Diseases named in the same sentence as TGFBR1 in open-access papers (continued):
Sharing a sentence is not in itself a finding about the gene and the disease.
TGFBR1 also shares sentences with these, for which no sentence is quoted: heart failure (6 papers); vascular Ehlers-Danlos syndrome (6); viral infection (6); genetic disorders (4); idiopathic pulmonary fibrosis (4); pancreatic ductal adenocarcinoma (4); Stroke (4); intrahepatic cholangiocarcinoma (3); kidney (3); leukoplakia (3); Osteopenia (3); Peritoneal Fibrosis (3); scleroderma (3); stomach cancer (3); Ureteral obstruction (3); anaplastic thyroid cancer (2); arrhythmogenic right ventricular cardiomyopathy (2); atrial fibrillation (2); Autoimmunity (2); B-cell lymphoma (2); brain tumors (2); carcinomas of kidney (2); cardiac diseases (2); Cerebral ischemia (2); coronary artery aneurysm (2); depression (2); dissection (2); dysplasia (2); Ehlers-Danlos syndrome (2); epitheliomas (2).
A further 148 diseases each share a sentence with TGFBR1 in 2 papers or fewer.